CXCR4 (C-X-C motif chemokine receptor 4)
Diseases named in the same sentence as CXCR4 in open-access papers (continued):
Sharing a sentence is not in itself a finding about the gene and the disease.
prostate carcinoma (continued). "The authors also determined that the SDF-1/CXCR4 signaling axis was key to prostate cancer cell homing to these regions, as osteoblasts express the SDF-1 ligand and prostate cancer cells express the CXCR4 receptor." (PMID 29867053, 2018). "The presence of CXCR4 has also been shown to correlate with metastatic disease in prostate cancer, where xenograft tumours that over expressed CXCR4 grafted into immunodeficient NOD/SCID mice exhibited increased growth, vessel density and metastasis." (PMID 29098360, 2018). "The role of other factors in homing to the bone is further supported by the partial inhibition of prostate cancer bone metastasis after the blockade of CXCR4." (PMID 29642534, 2018). "In 3D culture (made on Matrigel), CXCR4 expression was altered in prostate cancer cell lines, which regulate the metastatic process of prostate cancer cells." (PMID 29346265, 2018). "In a series of experiments by the Taichman group, osteoblast-derived CXCL12 (SDF-1) was found to mediate bone metastatic prostate cancer progression via binding of its receptor CXCR4 on the prostate cancer cells." (PMID 29867053, 2018). "Use of the CXCR4 inhibitor AMD3100 disrupted the preferential homing of prostate cancer cells to the lateral endocortical region of bone." (PMID 29867053, 2018). "In a prostate-cancer model, the use of a neutralizing antibody to CXCR4 also reduced the growth of prostate cancer cells injected intra-tibia and the subsequent formation of bone metastases." (PMID 29461491, 2018). "Of interest to future studies in sarcomas, silencing of CXCR4 axis contributions sufficed to compromise initial establishment of prostate cancers in bone microenvironment, whereas established bone tumors were sensitive only to RTK inhibitors." (PMID 29776413, 2018). "In the prostate cancers, high expression of CXCR4 enhances the invasive properties of tumor cells, while low expression levels decrease their metastatic efficiency." (PMID 30591657, 2018). "CSCs are known to overexpress GPCRs (e.g., CXCR4), which when stimulated in prostate cancer cells trigger growth, migration, and invasion." (PMID 28415604, 2017). "Several evidences indicated that CXCR4/SDF1 promoted prostate cancer cell invasion through MMP9 activation." (PMID 29108247, 2017). "We screened cells from our cell bank for the expression of chemokine receptors CCR7 and CXCR4 and found that PC-3 (human prostate cancer) cells express high levels of both CXCR4 and CCR7." (PMID 28432337, 2017). "In prostate cancer with bone metastasis, Treg cells expressing high levels of CXCR4 were recruited to bone marrow through an interaction with CXCL12, which is enriched in the bone marrow." (PMID 29379802, 2017). "Posteriorly, CXCL12 signaling through CXCR4 was shown to trigger the adhesion of prostate cancer cells to bone marrow endothelial cells by activating αvβ3 integrins." (PMID 27618899, 2016). "Recently published studies demonstrate synergistic effects of CXCR4 inhibition with chemotherapy in glioma, prostate cancer and leukemic mouse models." (PMID 27835905, 2016). "For example, CXCL12/CXCR4 was found to be a key regulator of tumor dissemination in cancer cells, including prostate cancer cells and it also plays an important role in the activation of prostate progenitor cells." (PMID 25978029, 2016). "To further explore the transactivation of HER2 by CXCL12, we investigated the role of small GTP protein Gαi2 in Src and HER2 phosphorylation in lipid raft membrane microdomains and the significance of CXCR4 in prostate cancer bone tumor growth." (PMID 27809841, 2016). "MiR‐150 targets CXCR4 in bone marrow‐derived mononuclear cells, and 18 miR‐494‐3p regulates CXCR4 expression in prostate cancer cells." (PMID 26871266, 2016). "Rosiglitazone (BRL), a PPARγ agonist used in type 2 diabetes treatment, has been shown to inhibit CXCR4 expression and to reduce the malignancy in colon, lung and prostate cancer cells." (PMID 27556298, 2016).
prostate carcinoma (continued). "The CXCL12/CXCR4 axis has been shown to be involved in metastasis of several types of cancers, including prostate cancers." (PMID 27809841, 2016). "Recently, it has been reported that activated PPARγ is able to reduce invasion and motility through CXCR4 downregulation in colon, lung and prostate cancer cells." (PMID 27556298, 2016). "The CXCR4/CXCL12 axis plays a central role in systemic metastasis of prostate carcinoma (PCa), thereby representing a promising target for future therapies." (PMID 27462860, 2016). "CXCL12 mediates the homing of cells that express CXCR4, and high levels of CXCL12 are associated with the preferential metastasis of prostate-cancer cells to the bone." (PMID 25884570, 2015). "CXCR7 is a key regulator of CXCR4-dependent motility, and we have previously shown that it is an androgen-sensitive microsomal protein in the LNCaP prostate-cancer cell line." (PMID 25884570, 2015). "Overall, gene expression analyses of clinical samples show that androgenic control of the CXCR4/CXCR7 axis becomes corrupted when normal prostate epithelial cells are transformed into organ-confined prostate-cancer cells." (PMID 25884570, 2015). "Androgens are known to induce CXCR4-dependent cell motility in prostate-cancer cells by upregulating CXCR4." (PMID 25884570, 2015). "CXCR7 expression was also required for CXCR4 homeostasis in LNCaP prostate-cancer cells, as CXCR4 protein levels were substantially reduced in the context of CXCR7 knockdown." (PMID 25884570, 2015). "In the context of human prostate cancer development, CXCR4 expression is higher in localized prostate-cancer cells than in the surrounding normal tissue." (PMID 25884570, 2015). "In prostate-cancer cells, androgens are known to stimulate expression of the CXCR4 mRNA and to repress that of the CXCR7 mRNA." (PMID 25884570, 2015). "Although CXCR4 is known to harbor N-linked glycans, future experiments will be required to unequivocally determine if CXCR7 is also N-linked glycosylated in prostate-cancer cells." (PMID 25884570, 2015). "In prostate cancer patients, CXCR4 expression is upregulated during cancer progression and aggressive cancer development." (PMID 24472670, 2014). "C-X-C chemokine receptor type 4 (CXCR4) is known to regulate lung, pancreatic and prostate cancer stem cells." (PMID 24583601, 2014). "It has lately been shown that phosphorylated ERG regulated expression of chemokine (C-X-C motif) receptor 4 (CXCR4) in prostate cancer cells." (PMID 24739220, 2014). "AR signaling was shown to activate CXCR4 protein expression through KLF5 in prostate cancer cells, propelling chemotactic migration in response to CXCL12, a chemokine abundantly present in the microenvironment and specific sites of metastasis." (PMID 24429391, 2014). "CXCL12/CXCR4 signaling has been shown to modulate the expression of angiogenic cytokines/chemokines in prostate cancer cells." (PMID 24472670, 2014). "Lentivirus-mediated CXCR4 RNAi reduced the expression of CXCR4 and tumor growth, and inhibited metastasis, particularly of bone metastasis of a prostate cancer cell line." (PMID 24647809, 2014). "Previous studies in pancreatic and prostate cancer stem cells also showed that stimulation of CXCR4 signalling increased the cancer stem cell fraction, while inhibition reduced stem cell activity (measured by the ability to form metastases)." (PMID 24583601, 2014). "Previous studies have shown that the chemokine receptor CXCR4 plays a role in breast and prostate cancer bone metastases via interactions with its ligand SDF-1." (PMID 24587095, 2014). "In the present study, the potential therapeutic effects of the CXCR4 antagonist were explored in a prostate cancer xenograft model." (PMID 24137439, 2013). "This concept is validated by studies showing that targeting CXCR4 function through neutralizing antibodies inhibited prostate cancer bone metastasis, and overexpression of CXCR4 in prostate cancer cells enhanced bone metastasis." (PMID 23902739, 2013).
prostate carcinoma (continued). "AMD3100 or other CXCR4-specific inhibitors should be developed and tested as therapies for human prostate cancer." (PMID 24137439, 2013). "The functional roles of CXCR7 are identified as CXCR4 does in many cancers, including prostate cancers." (PMID 24094005, 2013). "Using inhibitor assays, we demonstrate that regulation of the PI3K/Akt pathway by PTEN in turn regulates expression of both CXCL12 and CXCR4 in mouse and human prostate cancer cells." (PMID 23902739, 2013). "It is known that CXCR4 mRNA and protein are expressed in prostate cancer cell lines, including LNCaP, PC-3 and DU145, and in human prostate samples." (PMID 24137439, 2013). "The present study aimed to explore the potential therapeutic effects of a CXCR4 antagonist in prostate cancer." (PMID 24137439, 2013). "Current studies with Akt inhibitors implicate Akt as a key member in this pathway contributing to CXCR4 expression in prostate cancer cells." (PMID 23902739, 2013). "Our data confirm a role of SDF1α/CXCR4 in metastatic cascades of prostatic carcinomas and are consistent with an important role of MSCs in modifying cancer cells behaviour in the immediate cancer metastasis microenvironment." (PMID 23301946, 2013). "The G-protein coupled receptor (GPCR), Cysteine (C)-X-C Receptor 4 (CXCR4), plays an important role in prostate cancer metastasis." (PMID 23468933, 2013). "The chemokine CXCL12, also known as SDF-1, and its receptor, CXCR4, are overexpressed in prostate cancers and in animal models of prostate-specific PTEN deletion, but their regulation is poorly understood." (PMID 23902739, 2013). "Many prostate cancer cells express CXCR4 and osteoblasts, fibroblasts and endothelial cells in the bone marrow in turn express the ligand, SDF-1." (PMID 24213323, 2012). "The in vivo anti-growth and anti-metastasis activities of AMP were associated with induction of apoptosis and inhibition of proliferation of prostate cancer cells, reduction of prostate tumor angiogenesis, and reduction of CXCR4 expression." (PMID 22693649, 2012). "We confirmed increased expression of CXCR4 in prostate cancer cells grown under sphere forming conditions compared to monolayer conditions, and in CD44+/CD133+ prostate tumor initiating cells compared to CD44−/CD133− cells." (PMID 22359577, 2012). "To better understand self-renewal pathways in prostate cancer progenitors, we performed gene expression profiling and found that CXCR4 is highly expressed in prostate cancer cells grown as spheres." (PMID 22359577, 2012). "We then tested the effects of the CXCR4-specific small molecule antagonist AMD3100 on the survival of the progenitor population (CD44+/CD133+) within prostate cancer cell lines." (PMID 22359577, 2012). "This increased level of CXCR4 expression in the CD133+/CD44+ cell population suggests an important role for CXCR4 signaling in the maintenance of prostate cancer progenitors." (PMID 22359577, 2012). "Herein we report studies that suggest the CXCR4/CXCL12 axis is activated in prostate cancer progenitors and plays a role in self-renewal, differentiation potential, cell adhesion, and tumorigenicity." (PMID 22359577, 2012). "Next, we analyzed the relationship between CXCR4 expression and the self renewal capacity and tumorigenicity of prostate cancer progenitor cells." (PMID 22359577, 2012). "Conversely, blockade of CXCR4/CXCL12 interaction in prostate cancer cells via CXCR4 knockdown significantly inhibits bone metastasis in vivo." (PMID 22074556, 2011). "CXCL12 stimulates chemotaxis of metastatic prostate cancer cells expressing a high level of CXCR4 and accelerates their migration." (PMID 22074556, 2011). "Overexpression of CXCR4 in prostate cancer cells accelerated prostate tumor metastasis, prostate tumor vascularization, and tumor growth in vivo." (PMID 22074556, 2011). "Together, our findings indicate that Slug positively regulates MMP9 expression, possibly via CXCR4/CXCL12 pathway in prostate cancer cells." (PMID 22074556, 2011).
prostate carcinoma (continued). "Androgens promote migration of prostate cancer cells via KLF5-mediated upregulation of CXCR4 expression." (PMID 22074556, 2011). "In the case of prostate cancer dissemination, or homing, to the bone, CXCR4 (CXC receptor 4), CXCR7 and CXCR6 are believed to have the greatest impact and are discussed in the remainder of this section." (PMID 21603150, 2011). "MMP9 belongs to the matrix metalloproteinase family and is a target of the CXCL12/CXCR4 signaling in cancer cells, including prostate cancer." (PMID 22074556, 2011). "We found that SLUG positively regulates expression of the CXCL12/CXCR4 axis in human prostate cancer cell lines." (PMID 22074556, 2011). "Consistent with the qPCR and RT-PCR data, Western blot analysis confirmed that forced expression of SLUG increased CXCR4 protein expression in these four prostate cancer cell lines." (PMID 22074556, 2011). "MMP1 is also known to be upregulated by hypoxia and HIF-1a in breast and lung cancer cells, and also by CXCR4 in Nk cells and prostate cancer cells." (PMID 20102637, 2010). "In order to identify genes that are regulated by CXCR4 and contribute to the aggressive phenotype of CXCR4-expressing prostate cancer, we compared the expression pattern of various chemokines between CXCL12-stimulated and non-stimulated PC3-CXCR4.5 cells." (PMID 19340288, 2009). "Stromal-cell-derived factor-1-α presence has been shown to upregulate CXCR4 expression in the prostate cancer cell line PC-3." (PMID 19654580, 2009). "In order to determine the role of CXCR4 in the regulation of CCL20 production, we silenced CXCR4 by RNA interference in PC3-CXCR4.5 - prostate cancer cells with high CXCR4 expression." (PMID 19340288, 2009). "The effects of exogenous CXCL12 and CXCR4 antagonist AMD3100 on PC3 prostate cancer cells invasiveness were assessed in vitro and in vivo." (PMID 18983683, 2008). "We demonstrated previously that activation of CXCR4 by CXCL12 enhanced the adhesion of prostate cancer cells to bone marrow endothelial cells." (PMID 16859559, 2006). "The chemokine stromal derived factor-1 (SDF-1 or CXCL12) and its receptor CXCR4 have been demonstrated to be crucial for the homing of stem cells and prostate cancers to the marrow." (PMID 16859559, 2006). "Previously, we determined that the CXCL12/CXCR4 chemokine axis is activated in prostate cancers that metastasize to bone." (PMID 16859559, 2006). "One possibility is that the binding of CXCL12 to CXCR4 activates adhesion molecules that mediate the binding of prostate cancer cells to the bone marrow endothelium." (PMID 16859559, 2006). "Similarly, in prostate cancer, CXCR4 and CXCR2 contribute to bone metastasis, a common complication in advanced stages of the disease." (PMID 41024311, 2025). "SLUG promotes prostate cancer cell migration and invasion via CXCR4/CXCL12 axis." (PMID 39941741, 2025). "In prostate cancer, CXCR4 localises to the nucleus where its active signalling could be a mechanism for continuous CXCR4 activation in metastatic prostate cancer." (PMID 39982274, 2025). "Key search terms included: “G protein-coupled receptor”, “GPCR”, “prostate cancer”, “prostate carcinoma”, “castration-resistant”, “orphan receptor”, “chemokine receptor”, “CXCR4′′, “CXCR7′′, “hormone receptor”, “GnRHR”, “therapeutic target”, and “drug discovery”." (PMID 41347146, 2025). "CXCL12/CXCR4 pathway biological axis is an important regulator of the spread of prostate cancer." (PMID 41347146, 2025). "Additionally, Mozobil (another name for AMD3100) has been shown to block CXCR4 signaling, preventing tumor metastasis in various cancer models, including breast and prostate cancer." (PMID 41024311, 2025). "CD45 depleted CTC-enriched fractions expressing CXCR4, and the alpha-chemokine receptor specific for stromal-derived-factor-1, isolated from the PB of prostate cancer patients through the CellSearch® platform, documented poor prognosis in patients treated by radiotherapy." (PMID 39335650, 2024).
prostate carcinoma (continued). "PIM1, a serine/threonine protein kinase, can directly bind to CXCR4 and facilitate its membranous expression, whereas the elevated co-expression of these two proteins, PIM1 and CXCR4, was correlated with aggressiveness and poor prognosis in prostate cancer patients." (PMID 39465008, 2024). "Recently, CXCR4-positive CTCs were shown to persist in the blood of prostate cancer patients treated with radiotherapy for up to 3 months, suggesting that CXCR4-positive CTCs may represent aggressive CTC subclones that contribute to treatment resistance." (PMID 38727318, 2024). "CXCR4/CXCL12 also plays a crucial role in bone metastasis of prostate cancer." (PMID 38464516, 2024). "Advanced prostate cancers exhibit increased expression of GPCRs such as CXCR4, LPAR1-3, and PAR-1." (PMID 39000269, 2024). "However, knockdown of CXCR4 significantly reduced the migration and invasion of prostate cancer cells into osteoblasts, thereby improving bone metastasis." (PMID 37497001, 2023). "Their study revealed that Luteolin, Ellagic Acid, and Punicic Acid inhibited growth and metastasis in the C-X-C motif chemokine ligand 12 (CXCL12)/C-X-C chemokine receptor type 4 (CXCR4) axis in human prostate cancer xenograft tumors in severe combined immunodeficiency mice." (PMID 36992138, 2023). "CXCL12/CXCR4 signaling promote initial establishment of prostate cancer colonization in bone microenvironment by actively competing with osteoblastic niche and these interactions along with cross talk with bone microenvironment factors promoting bone tumor growth." (PMID 37996444, 2023). "In in vitro studies using prostate cancer cell lines, rosiglitazone might inhibit the migration and invasion of prostate cancer cells through its inhibitory effect on the CXCR4/CXCL12 axis and downregulation of vascular endothelial growth factor." (PMID 37560306, 2023). "In addition, hypermethylation of the HIC1 exacerbated prostate cancer metastasis by inducing epithelial-mesenchymal transition (EMT) mediated by Slug and CXCR4, which contributed to the poor prognosis of prostate cancer patients." (PMID 37388742, 2023). "Here we are extending our previous observations that chemokine receptor CXCR4 indirectly forms an endogenous complex with PI4KIIIα with adaptor proteins in prostate cancer cells, and this interaction is ligand-dependent thus, CLCL12/CXCR4 axis induces the production of PI4P." (PMID 37996444, 2023). "CXCR4 is a crucial regulator of prostate cancer invasiveness and metastasis development." (PMID 36863017, 2023). "In addition, in prostate cancer, a mechanism has been described as leading to a translocation of CXCR4 to the nucleus, where it remains functional, ultimately resulting in increased metastatic potential and limited prognosis." (PMID 36982302, 2023). "Together, these findings highlight an important role for CAF-derived CXCL12 during tumor progression and chemoresistance, and indicate that inhibition of the CXCL12/CXCR4 signaling axis may chemo-sensitize prostate cancer cells." (PMID 36671452, 2022). "LncRNA UCA1 can regulate CXCR4 expression in prostate cancer cells to affect their progression." (PMID 35773731, 2022). "In prostate cancer cells, CXCR4 has previously been characterized as a target gene of miR-494-3p." (PMID 36003502, 2022). "Interestingly, CXCL12 has also been shown to facilitate adhesion of prostate cancer cells expressing CXC receptor 4 (CXCR4) to endothelial cells and ECM proteins via α5β3 integrin to facilitate tumor dissemination." (PMID 36671452, 2022). "As the first study to elucidate the molecular mechanisms underlying ERK1/2 activation by OR51E2, we focus on three important signaling molecules: Gβγ, PI3Kγ and ARF1, which we have recently demonstrated to control CXCR4-mediated ERK1/2 activation in prostate cancer cells." (PMID 36313302, 2022).